ATM (ATM serine/threonine kinase)
Diseases named in the same sentence as ATM in open-access papers (continued):
Sharing a sentence is not in itself a finding about the gene and the disease.
tumor (continued). "Both models depict the same history for the metastatic branch, but different tumour initiation: SCITE places the ATM mutation on top of the clonal mutations, which appear ordered in a linear chain of 34 events." (PMID 31023236, 2019). "Preclinical data showed that GC cells with ATM deficiency were associated with olaparib sensitivity; approximately 10–20% of GC tumor samples exhibit low or undetectable ATM expression by IHC." (PMID 31632839, 2019). "We found that ATM-associated tumours belong mostly to the luminal B subtype, are tetraploid and show LOH at the ATM locus at 11q22–23." (PMID 29665859, 2018). "The ataxia telangiectasia mutated (ATM) tumor suppressor frequently displays loss-of-function mutations or is deleted in PTCL." (PMID 29148847, 2018). "With respect to the IHC of tumours arising in ATM variant carriers, 97% of ATM-associated tumours were ER+, which was significantly higher than the proportion of ER+ tumours in the PICBIM series (59%, P = 0.004)." (PMID 29665859, 2018). "We have recently demonstrated that human Treg cells and tumor cells can also induce ATM-associated DNA damage in responder T cells resulting in T cell senescence." (PMID 29625565, 2018). "Because ‘two-hit’ inactivation of the causative gene is regarded as a principal feature of molecular pathogenesis of most hereditary tumours, we next examined the LOH status of ATM-associated tumours at 11q22–23 in the tumours from HetAT participants." (PMID 29665859, 2018). "As an example, tumor 014P had a chr11:108098576_C/G variant in ATM with an ALT:REF allele ratio of 0.9 in the germline but 2.8 in the tumor due to LoH." (PMID 30062048, 2018). "The somatic aneuploidy allowed pathogenic germline variants (e.g., ATM) to be expressed unopposed, with RNA expression patterns showing inactivation of downstream tumor suppressor pathways." (PMID 30062048, 2018). "In another study by the same group, ATM was also associated with tumours with unstable genome or the BRCA mutational signature." (PMID 29329208, 2018). "a Genome-wide view of cumulative CNVs present in the 19 ATM-associated tumours from participants carrying one or two copies of a TV." (PMID 29665859, 2018). "The two ATM somatic variants identified in tumours T0015 and T0077-L were predicted as benign variants according to the Align-GVGD prediction tool." (PMID 29665859, 2018). "Sanger sequencing of the tumour-blood DNA pairs suggested that the ATM wild-type allele was lost in all tumours that underwent LOH at this locus (data not shown)." (PMID 29665859, 2018). "Despite the very limited sample size, we found that at the somatic level, ATM-associated tumours were more homogeneous in terms of CNV than in terms of SNV." (PMID 29665859, 2018). "The tumor suppressor role of ATM is highlighted by the frequent somatic mutations of ATM in many lymphoid malignancies." (PMID 30662441, 2018). "Functional studies of the cellular activity of ATM in individuals who carry these variant alleles will aid in further elucidating their anti-tumour properties." (PMID 29433565, 2018). "Like BRCA2- and CHEK2-associated tumours, ATM-associated tumours are mostly luminal tumours but they do not show a particular histological subtype as observed in BRCA1- (medullary), BRCA2- (lobular), CDH1- (lobular), and PTEN-associated tumours (apocrine)." (PMID 29665859, 2018). "This analysis confirmed that loci 8p21, 13q14, 16q13-q24, 17p13-p12 and 21p11 were sites of recurrent alterations found in ≥ 70% of ATM-associated tumours." (PMID 29665859, 2018).
tumor (continued). "On the basis of our analysis of high-confidence SNVs identified in each ATM-associated tumour genome, we next looked for potential driver mutations." (PMID 29665859, 2018). "ATM-associated tumours also differ from luminal BRCA2-associated tumours, which can also display the HRD signature." (PMID 29665859, 2018). "The role of ATM or RB1 mutations as potential predictive or prognostic biomarkers has been reported in different tumor studies." (PMID 29682192, 2018). "Other studies have shown a relationship between high expression of PI3K or PTEN-deficient tumor cells with increased response to ATM pathway inhibition." (PMID 29340025, 2017). "We subsequently identified 8 patients with truncating mutations in ATM who received radiotherapy to gross disease and had tumor sequencing performed." (PMID 28055970, 2017). "The likely evolutionary advantage of mutations or loss of BRCA2 and ATM in CRPC is that they act as tumour suppressors in the CRPC." (PMID 28851861, 2017). "In summary, we report that loss of ATM expression, as denoted by a low ATM-EI within the malignant component of a tumour, can be detected in a substantial proportion of resected NSCLCs." (PMID 28418844, 2017). "Genomic aberrations such as abnormal upregulation of host miRNAs (miR-27b-3p, miR-26a-5p, miR-30b-5p, miR-19b-3p, and miR-92b-3p) targeting ATM would favor proliferation, tumor cell survival and occurrences of mutations that would favor oncogenesis." (PMID 29132323, 2017). "Tumor cells show altered expression of key DNA damage repair genes such as ataxia telangiectasia mutated (ATM), which drives the proliferation of genetically unstable tumor cells." (PMID 29137421, 2017). "Targeted sequencing analysis of the tumor revealed a frame-shift mutation in ATM, a gene centrally involved in the DNA damage response." (PMID 28055970, 2017). "Targeted sequencing analysis of the tumor identified a somatic frame-shift mutation in ATM, a gene known to be associated with radio-sensitivity in the germline." (PMID 28055970, 2017). "In this study, we examined the role of ATM, the gene mutated in ataxia telangiectasia, in the tumor suppressive action of miR-203a in GBM." (PMID 29348882, 2017). "Such loss of ATM is seen in many stage I tumours, implying that this is a relatively early event in NSCLC tumourigenesis." (PMID 28418844, 2017). "Whilst neither AZD6738 (daily × 14) nor cisplatin (days 1 and 8) alone caused significant tumour growth delay, the combination inhibited tumour growth by 75.5% and this effect was greater in ATM deficient tumours (84.8%)." (PMID 28448462, 2017). "A low ATM-EI represents a tumour sample in which the tumour portion is ATM deficient relative to the surrounding stromal cells." (PMID 28418844, 2017). "As we determined that ATM-deficient tumors have more widespread DNA damage than ATM-proficient tumors, we examined the extent of chromosomal alterations (an indicator of genome instability) in our established KC and KCATMΔΔ tumor cell lines using SKY analysis." (PMID 28894253, 2017). "The gene, known as the Ataxia Telangiectasia Mutated (ATM) is a tumor suppressor gene which encodes a protein that signals DNA damage." (PMID 27449094, 2016). "In this study, the authors starting from a synthetic lethal screen, demonstrate that tumor cells with mutations in ATM exhibit increased sensitivity to MEK1/2 inhibition through the modulation of the AKT/mTOR pathway." (PMID 27922010, 2016). "Screens based on short interfering RNA (siRNA) have identified several genes, such as ataxia-telangiectasia mutated (ATM), that when deleted sensitize tumor cells to PARP inhibitors." (PMID 27613518, 2016).
tumor (continued). "The minimal deleted region is known to encode several tumor suppressor genes including ATM which plays an important role in cell cycle regulation." (PMID 27110362, 2016). "This is seen in the high frequency of TpC* mutations in potential “driver” mutations, including missense TpC* mutations in well-known genes such as KMTD2 and ATM shared across all tumours of a patient." (PMID 26553077, 2015). "Recently, two novel potential therapeutic approaches to specifically treat ATM-deficient neoplastic disease have emerged from in vitro and in vivo experiments performed in different laboratories." (PMID 26113859, 2015). "CCDC6 gene product is a pro-apoptotic protein substrate of ATM, whose loss or inactivation enhances tumour progression." (PMID 25885523, 2015). "To further test if loss or increase of p-ATM expression was related to increase in tumor thickness, we classified our database on the basis of tumor thickness ≤ 2 mm or > 2 mm and analyzed the correlation." (PMID 26275218, 2015). "We highlight key aspects of ATM loss in murine tumour biology and demonstrate that this model faithfully recapitulates subtypes of human PDAC." (PMID 26220524, 2015). "In the NB110 tumor set, ATM mRNA levels were significantly reduced in the specimens carrying loss of ATM." (PMID 26053094, 2015). "ATM has previously been shown to harbor somatic mutations in over 50% of sequenced tumor samples from patients with the T-PLL subtype of PTCL." (PMID 26536348, 2015). "Significant, tumour-specific loss of heterozygosity occurs in nine genes (ATM, BAP1, BRCA1/2, BRIP1, FANCM, PALB2 and RAD51C/D)." (PMID 26689913, 2015). "These somatic mutations were largely missense, and in many cases, ATM behaved like a tumor suppressor." (PMID 25247188, 2014). "For example, loss of ATM results in a decreased expression of the tumor suppressive miRNAs, miR- 96, which is known to target KRAS, and the miR-29 family, which includes miR-29b-1, miR-29b-2, and miR-29c." (PMID 23741392, 2013). "Multivariate analysis using variables of depth of tumor, lymph node status, Lauren’s classification of histologic type, adjuvant chemotherapy, ATM intron mutation, and ATM protein expression was performed." (PMID 24324828, 2013). "NF-κB signaling by ATM has been linked to immune system development, DNA repair, tumor progression, and defects in the nuclear lamina." (PMID 23532176, 2013). "ATM mutation and ATM protein loss had characteristics of old age, distal location of tumor, large tumor size, and histologic intestinal type." (PMID 24324828, 2013). "GC patients with ATM gene mutation were associated with old age, large tumor size, distal location, intestinal type, deeper invasion, and lower recurrence rate." (PMID 24324828, 2013). "Utilizing the TAM tool for annotating miRNAs and the human miRNA disease database, we identified 4 repressed miRNA tumor suppressors and 7 over-expressed oncomirs in the ATM-deficient cells (for examples)." (PMID 23741392, 2013). "A potential target of miR-181 is the serine/threonine kinase Ataxia telangiectasia mutated (ATM) which acts as a tumor suppressor." (PMID 23860207, 2013). "Univariate Cox regression modelling showed that worse survival was associated with reduced expression of ATM in tumours as compared to normal tissue (HR=1.56, 95% CI 1.05-2.33, p=0.028)." (PMID 23154512, 2012). "The tumor suppressor function of ATM has been linked to its role in DNA repair and checkpoint function." (PMID 21980358, 2011).
tumor (continued). "After radiation, increased activation of Ataxia-Telangiectasia Mutated (ATM) kinase pathway has been reported in glioma stem cells andCD133-positive atypical teratoid/rhabdoid tumor cells." (PMID 21935375, 2011). "In sum, we have identified CHK1 inhibition as a strategy for targeting FA deficient tumor cells, especially when combined with cisplatin treatment or ATM inhibition." (PMID 19371427, 2009). "Because deficiency in the FA pathway is not lethal, specific inhibitors are expected to display low toxicity toward normal cells but kill tumor cells deficient in ATM or other genes with synthetic lethal relationships to the FA pathway." (PMID 20043851, 2009). "Clinical studies support synthetic‐lethal sensitivity to ATR inhibition in ATM‐deficient tumours." (PMID 41537447, 2026). "This suggests that DNA-PK inhibitors may have anticancer activity as monotherapy in ATM-deficient tumours, which is supported by preclinical data." (PMID 40382524, 2025). "In two of the three patients with pathogenic variants, the ATM protein was absent from the MM tissue, which supports the hypothesis that the loss of ATM’s tumor suppressor function may contribute to MM development." (PMID 41331641, 2025). "A second extension could include synthetic lethal interactions with PARP and ATR inhibitors beyond BRCA loss and HRD, such as ARID1A and ATM mutations, which would further help identify tumours most likely to respond to specific treatments." (PMID 39875558, 2025). "Importantly, in vivo xenograft models confirmed the antitumor efficacy of AZD6738, demonstrating significant tumor growth inhibition and increased apoptosis in ATM-deficient tumors." (PMID 40869030, 2025). "This dual profile may also inform treatment, as ARID1A-deficient tumours respond to DNA-damaging agents and immune checkpoint inhibitors, while ATM loss may sensitize tumours to PARP or ATR inhibitors." (PMID 41146957, 2025). "Otherwise, RT causes the release of irradiated tumor-cell-derived microparticles, which induce double-strand breaks (DSBs) and activate the ATM/ATR/CHK1 and the downstream JAK-STAT signaling pathways, leading to the upregulation of MHC-I in non-irradiated tumor cells." (PMID 40565309, 2025). "Tumors that have ATM mutations or reduced ATM protein levels may exhibit an altered DNA damage response, potentially leading to increased genomic instability and a higher tumor mutation burden (TMB)." (PMID 40310425, 2025). "Importantly, compound also showed some single-agent efficacy, a novel finding for selective DNA-PK inhibitors, as it achieved tumour regressions in both ATM-deficient and ATM wild-type models." (PMID 40256842, 2025). "The loss of ATM impairs these functions and may lead to genomic instability, tumor development, and an increased reliance on PARP; this opens the door to targeted therapies, such as PARP inhibitors." (PMID 41301029, 2025). "The biological function may be linked to an alteration in the ATM region, which is crucial for its activation and tumor suppressor activity." (PMID 40004552, 2025). "Because these interactions are crucial for an effective anti-tumor immune response, ATM deficiency may modify them." (PMID 40310425, 2025). "Loss of SLFN11 promotes tumor cell proliferation by restoring ATM expression." (PMID 40766331, 2025). "In preclinical models it potentiated cisplatin and irradiation, particularly in ATM-deficient settings, by preventing G2 arrest and repair and forcing lethal mitosis; combinations with cisplatin or topotecan produced deeper tumor regressions than chemotherapy alone." (PMID 41190241, 2025).
tumor (continued). "While the presence of high frequencies of TERT promoter mutations in metastatic PTCs was already demonstrated to be associated with tumor aggressiveness, the enrichment of ATM pathogenic mutations in the LNMs of PTC patients with 4 or more DMs observed in this study is noteworthy." (PMID 39030377, 2024). "Our study was not sufficiently powered to determine whether a variant allele fraction or tumor biopsy site (brain metastasis vs primary tumor vs extracranial metastasis) influences the effects of ATM variants on post-SRS outcomes." (PMID 38260227, 2024). "Our patient’s tumor contained a LOF ATM mutation, which occurs in only 3% of pRCC." (PMID 39156348, 2024). "Both types of ATM alterations could potentially influence tumor control, whereas germline variants found in normal tissues are thought to play a more important role in the pathogenesis of RN compared with tumor cell ATM variants." (PMID 38260227, 2024). "Additionally, a study revealed that ATR inhibition enhances the anti-tumor activity of cisplatin in ATM-deficient tumor cells." (PMID 38807759, 2024). "Furthermore, loss of expression in the DNA repair gene ataxia telangiectasia mutated (ATM) is reported in up to 22% of tumours." (PMID 38135713, 2024). "The disruption of the DNA damage response pathway in the present tumor is also reinforced by the pathogenic variant found in the ATM gene, which could affect its expression, impacting on the patient survival." (PMID 37107676, 2023). "Moreover, the loss of ATM is correlated with a low degree of tumor differentiation and notable increase in lymph-node metastasis, critically affecting patient survival." (PMID 37674118, 2023). "It has been shown that cytoplasmic leakage of mtDNA is the major source of cytoplasmic dsDNA in ATM-deficient tumor cells, suggesting that mtDNA may play an important role in the innate immunity of tumor cells." (PMID 37965570, 2023). "Moreover, the change in both MCPH1/BRIT1 and ATM together was significantly associated with an increased in tumour grade." (PMID 36845691, 2023). "This has offered a therapeutic vulnerability that has been extensively explored clinically in BRCA1/2 mutant patients but is now also being examined as a viable therapy in tumours with other specific genotypes, including those presenting with ATM, PALB2, RAD51C, and RAD51D mutations." (PMID 36980782, 2023). "From a total of 6830 tumor samples from 6527 individual patients that underwent tumor DNA sequencing, 584 unique tumor variants were identified in the gene list of interest (ATM, BRCA1, BRCA2, MLH1, MSH1, MSH6, PALB2 and PMS2) from 503 unique tumor samples/patients during the study period." (PMID 36261688, 2023). "And our observations demonstrated that CTPS2 could promote CLL cell survival through DDR pathway, suggesting an underlying molecular mechanism by which ATM functions as a tumor suppressor." (PMID 36635772, 2023). "Also using PARPi synergy with the ICIs in tumours with homologous recombination damage reported increases in the mutational load in tumour cells and increased expression of PD-L1 by ATM-ATR-Checkpoint kinase 1 pathway." (PMID 36845691, 2023). "ATM has bi-allelic loss rates between 40 and 77% among these six tumour types." (PMID 34979999, 2022). "The authors finally suggested that loss or reduced expression of the genes for the BRCA1-A complex and of the NHEJ components Ku70/80, XRCC4, XLF, and LIG4 in ATM-deficient tumours could explain resistance to PARPi in some cases." (PMID 35681784, 2022).